MAP2 (microtubule associated protein 2)
Diseases named in the same sentence as MAP2 in open-access papers (continued):
Sharing a sentence is not in itself a finding about the gene and the disease.
tumor (continued). "The expression of EPHB2, IL-13, MAP2, RPN2, and TRAF5 was correlated with microsatellite instability (MSI), while the expression of IL-13, RPN2, and TRAF5 was related to tumor mutation burden (TMB)." (PMID 33937013, 2021). "The result of immunofluorescence showed that these tumor spheres were able to differentiate into MAP2+ neurons, O4+ oligodendrocytes and GFAP+ astrocytes." (PMID 33614649, 2021). "Xenograft tumor of HCT 116 showed an increased expression of neuronal genes MAP2 and SYN1, neural stemness genes CDH2, MSI1, NCAM1, SOX2/9, VIM and ZEB2, and genes for mesodermal and endodermal tissues (ACP5, AFP, DESMIN, HNF4A and KRT8)." (PMID 33468253, 2021). "Large areas of intense staining of SOX1, SOX9 and MAP2 suggested that cells with neural stemness and neuronal features were among the major cell types in tumor." (PMID 33468253, 2021). "Meanwhile, high expression of NR6A1 and MAP2 was positively correlated with lymph node involvement, and high E‐cadherin expression level was negatively correlated with lymph node involvement, tumor size, and metastasis." (PMID 33034957, 2020). "By knocking down MAP2 it has been revealed that these undifferentiated cells generate functional autonomic neurons that stimulate tumor growth." (PMID 32555170, 2020). "A panel of neuronal genes, such as DCX, NEURONG2, MAP2, NEUROD1, were upregulated with FTT treatment for 2 or 10 days, while tumor associated genes downregulated." (PMID 30837577, 2019). "Consistently, the tumorigenesis capacity of the human CSCs and the tumor growth in nude mice were markedly reduced by MAP2 shRNA1 and slightly knocked down by MAP2 shRNA2." (PMID 29263908, 2017). "Accordingly, we ablated the neural generating capabilities of the human CSCs by MAP2 RNAi (5′ end RNAi: shRNA1 and 3′ end RNAi: shRNA2) to explore the involvement of neurons derived from the human CSCs in tumor progression." (PMID 29263908, 2017). "This was accomplished by immunostaining tissue samples collected out of all three tumor zones from each patient individually using specific antibodies against Map2 and CD34." (PMID 25609379, 2015). "There was strong immunoreactivity for GFAP and OLIG2 in many tumor cells, while all tumor cells expressed S-100 and MAP-2." (PMID 25955030, 2015). "To distinguish between these possibilities we stained frozen tumor sections with nestin, MAP2, PDGFRβ, and β-catenin specific antibodies." (PMID 22891161, 2012). "In this study, resistant tumours exhibited a higher expression of several growth factors, growth factor receptors, the PI3K regulatory subunit p85, microtubule-associated protein 2, and some basal genes." (PMID 19755993, 2009). "We found that protein extracts from both tumours differed in their proteolytic activity on rat brain MAP2." (PMID 10945505, 2000). "Given its upregulation in NCB tumors across inhouse and public dataset, we hypothesized that MAP2 might promote cytoskeletal remodeling, enabling tumor cell plasticity and evasion of VEGF and PARP inhibition." (PMID 41256002, 2025). "Notably, we found NES+ and SOX2+ tumor cells in closer proximity to PDGFRβ+ regions, in comparison to MAP2+ cells." (PMID 40562749, 2025). "Invasive tumor glands revealed at least focal MAP2 expression in 86% of the cases." (PMID 38310601, 2024). "The expression of Ki-67 was reduced, and that of MAP2 was highly upregulated in tumor tissues." (PMID 37375824, 2023). "All tumor samples expressed MAP2, suggesting that MAP2 may be a biomarker for identifying tumors with neural origins or those with significant neural involvement." (PMID 36230740, 2022). "CD271, MAP2, and Ki67 were used to visualize the tumor regions by immunofluorescence." (PMID 35835937, 2022). "Moreover, NSC11 and NSC20 tumor cells in the OB showed a higher number of contacts with MAP2+, TH+ and GABA+ neurons." (PMID 36482431, 2022).
tumor (continued). "To verify the glioneuronal architecture, we first stained BRAFV600E/AktDD brain slices with antibodies against the glial fibrillary acidic protein (GFAP) and microtubule-associated protein 2 (MAP2) and found a strong immunoreactivity for both markers within the tumor area." (PMID 36538906, 2022). "Therefore, both GFAP and MAP2 cells were found to be targeted by the IUE approach within the tumor parenchyma." (PMID 36538906, 2022). "Furthermore, the outer tumor cell layer in ACP showed distinct expression of the neuroepithelial marker MAP2 compared to PCP35, which corresponds to our MS results." (PMID 34707096, 2021). "Tumor cells use matrix metalloproteinases 2 and 9 (MMP2 and 9) during invasion causing tumor dynamic changes; additionally, MAP2 is a major regulator of microtubule dynamics in neuronal cells and other cell types, and is associated with cell migration in epithelial cells." (PMID 30696040, 2019). "A significant difference in the number of Map2-positive cells could be seen between all three tumor zones: the farther from the center of the main tumor mass, the fewer the Map2 expressing cell number identified." (PMID 25609379, 2015). "Therefore, both the CD34-staining and the Map2-staining demonstrated histopathological differences between the three tumor zones." (PMID 25609379, 2015). "This combined therapy, significantly delayed the initial onset of tumor growth for both phenotypes, but resulted in the emergence of newer phenotypes as evident from the presence of unique/unfamiliar populations of MAP2+ and PDGFRβ+ cells." (PMID 22891161, 2012). "In addition, histopathological examinations of the whole block sections revealed rather a small-scale expression heterogeneity with positive and negative areas close to one another, thereby raising the detection probability of MAP2-positive tumor areas even in the TMA setting." (PMID 38310601, 2024). "MAP2 expression in some tumor areas could indicate a more mature neuronal phenotype." (PMID 33671521, 2021). "When the tumor sizes were compared, the differences among the six groups were not significantly different and IHC examination of stem cell (Nestin), neural (MAP2), glial (GFAP), cell proliferation (Ki67), and mitochondrial markers failed to reveal major differences as well." (PMID 34719887, 2021). "We identified tumor RG-like (NEShigh; SOX2+), NProg-like (NESlow/−; SOX2+) and Nb-like (SOX2−; MAP2+) cells in protein staining." (PMID 40562749, 2025). "Through the fusion, the GFP+/c-MYChigh cells of the tumor sphere encountered contact to astrocytic cells (GFAP+) and neurons (MAP2+) from the outer edge of the organoid." (PMID 40917877, 2025). "Therefore, our findings may open new avenues towards a more sophisticated tumor classification by modifying classical haematoxylin–eosin (HE) based tumor classification procedures by immunohistochemical parameters such as expression of MAP2." (PMID 38310601, 2024). "The expression of AmotL2 in ENS cells was evidenced by co-immunostaining with MAP2 and GFAP markers in non-tumor colon sections from untreated and OxPt-treated patients." (PMID 39335466, 2024). "MAP2 was pronouncedly expressed both in high-grade PIN lesions and in adjacent invasive tumor areas." (PMID 38310601, 2024). "Because tumor tissue contains more cells than PTME, we also quantified MAP2 immunoreactivity by measuring the fluorescence intensity outside the DAPI-positive regions." (PMID 36538906, 2022). "The expression of MAP2, DYNC1H1, and MKI67 was obviously higher expressed in tumor tissues, while CPS1 and PTPRB were downregulated in tumor tissues compared with normal tissues in TCGA dataset." (PMID 35311113, 2022).
tumor (continued). "Further immunostaining against the somatodendritic marker MAP2 was used to depict the neuropil in the control and BRAFV600E/AktDD tumor tissue." (PMID 36538906, 2022). "Quantitative real-time PCR (qRT-PCR) exhibited that expression of CPS1 and PTPRB was downregulated in tumor tissues compared with paracancerous tissues, while MAP2, DYNC1H1, and MKI67 were overexpressed in tumor tissues." (PMID 35311113, 2022). "Gene expression comparison between U-118 MG cells and the tumor showed an increased expression of neuronal and neural stemness genes MAP2, NEUN, ROBO2, PAX6, ZIC1, ZEB2, as well as MYC and OCT4 in tumor." (PMID 33468253, 2021). "Compared with A375 cells, A375 xenograft tumor displayed an upregulation for glial and neuronal genes (GFAP, BDNF, MAP2, MTURN, ROBO2, SYT1 and TUBB3) and neural stemness genes (ASCL1, MSI1, PAX6, PDGFRA, SOX9, VIM, ZIC1/2)." (PMID 33468253, 2021). "The neoplasm was mainly composed of round, uninucleate cells with hyperchromatic nuclei, which were immunopositive for OLIG2, doublecortin, MAP2, synaptophysin, and vimentin, indicating components of both oligodendroglial and neuronal differentiation." (PMID 34977226, 2021). "Immunofluorescence showed that these tumor spheres were able to differentiate into GFAP+ astrocytes, MAP2+ neurons, and O4+ oligodendrocytes." (PMID 32843056, 2020). "Bioinformatics analysis of TCGA data revealed that the expression levels of a panel of neuronal genes in GBM were significantly lower than those in non-tumor tissues, and patients with high NEUROD1 or MAP2 expression had a better outcome." (PMID 30837577, 2019). "The immunohistochemical staining in this study showed that the tumor cells experssed synaptophysin, NSE, MAP-2 and S-100 in two cases." (PMID 28977976, 2017). "A novel tumor stem cell niche (CD133 and CD44), a specific cellular environment at the brain invasion border (TNC and MAP2) and a novel role for pituitary stem cells in the pathogenesis of adaCP has been proposed." (PMID 26927026, 2016). "Quantification of both intensity of the ICG signal and density of Map2-expressing tumor cells in these cases showed significant differences in the extents of ICG fluorescence and Map2-staining." (PMID 25609379, 2015). "We also observed that a number of genes with tumor suppressor function (GPRC5A, ELF1, NAB2, Sema4D, ACPP, MAP2, RUNX1) persistently remained downregulated in response to radiation exposure." (PMID 23216862, 2012). "Cells in both tumor models retained proliferative and immature characteristics, as evidenced by c-MYC overexpression and increased MKI67 expression, and decreased expression of MAP2 and GFAP compared to their respective controls." (PMID 40917877, 2025). "The tumor cells expressed NSE and cytokeratin AE1/AE3, but were immunohistochemically negative for synaptophysin, chromogranin A, calcitonin, S-100 protein, GFAP, NFH, and MAP-2, which in our opinion supports the diagnosis of NEC." (PMID 39974159, 2025). "According to the neuron marker MAP2, which identifies all the mature neurons, NSC11 and NSC20 cells in the OB had a significantly greater frequency of soma-soma contact with neurons as compared to the tumor cells in the RH." (PMID 36482431, 2022). "The tumor cells lacked astrocytic processes while focal areas, immunohistochemically positive for glial fibrillary acidic protein (GFAP) and microtubule-associated protein 2 (MAP2), were interpreted as entrapped preexistent central nervous system tissue." (PMID 35198980, 2022). "The best ones were Lt-MAP2, effective against bacteria and tumor cells, and Lt-MAP3, active against resistant and non-resistant bacterial strains." (PMID 36212827, 2022). "Many tumor cells expressed GFAP and MAP2 in the cytoplasm and in processes." (PMID 35198980, 2022).
tumor (continued). "Immunofluorescence staining of AQP1, CXCR4 and MAP2 of the primary tumor revealed AQP1 expression in some but not all tumor areas, as well as staining of vascular structures in which AQP1 occurs physiologically." (PMID 33671521, 2021). "IHC revealed expression of Sox1, Sox9, Map2, Acta2, Bglap and Afp in sections, indicating the presence various types of neural and non-neural tissues or cells in tumor." (PMID 33468253, 2021). "Additionally, RT-PCR also indicated the gene expression of iPSC-derived tumor tissue in three germ layers, demonstrating expressions of GATA4 in endoderm; HAND1 and GATA6 in mesoderm; and TUBB3, MAP2, and GFAP in ectoderm." (PMID 33224204, 2020). "Expression of mature neuronal markers MAP2 and SYP were seen in isolated xenograft tumor cells." (PMID 29774098, 2018). "The tumor cells and lipidized cells of liponeurocytoma may express the neuronal markers such as synaptophysin, NSE and MAP-2." (PMID 28977976, 2017). "Otherwise, this tumor was positive for Cam5.2 and MAP-2 and negative for EMA, GFAP and synaptophysin." (PMID 27229317, 2016). "On the other hand, the expression of CD166, CD133, CD44, A2B5, CD56, NGFR and DCX seemed to be higher in UA cells, but also not statistically significant, while the expression of CD9, Nestin, GFAP, CD24, PDGFRb, PDGFRa, MAP2, TUBIII, S100 were consistently high in both UA and tumor core samples and." (PMID 27605047, 2016). "Under neural differentiation conditions, cells from sphere cultures of both UA and tumor core samples gave rise to cells that expressed markers of mature neurons and glial cells (MAP2, β-TubIII and GFAP), but not oligdendrocytes (O4)." (PMID 27605047, 2016). "The combined effects were remarkably more suppressive on tumor growth and also concurrently prevented the AD phenotype from establishing itself in early stage tumor formation as defined by the absence of MAP2+ cells irrespective of AD or AI inoculation." (PMID 22891161, 2012). "The presence of both neurons and astroglia cells, respectively, within the tumours has been verified by immunofluorescence using antibodies against MAP2 and GFAP, which confirmed the observation of the reduced numbers of both types of cells in the transchromosomic tumours, compared to controls." (PMID 18047653, 2007). "MAP2-negative tumor glands (GP 4) were found in 19.4% of the cases." (PMID 38310601, 2024). "MAP2-negative tumor glands (GP 3) were found in 13.6% of the cases." (PMID 38310601, 2024). "Immunohistochemically, tumor cells reveal positivity for GFAP only, while they are negative for MAP2, OLIG2, and CD34." (PMID 38544524, 2024). "The tumor was difficult to diagnose, exhibiting GFAP and SOX10 negative and MAP2 positive." (PMID 41331048, 2025).
infection (52 papers, 2010 to 2025). The state of being infected such as from the introduction of a foreign agent such as serum, vaccine, antigenic substance or organism. "The downregulation pattern in the MAP-2 has already been observed under pathogenic infection of RABV." (PMID 35685339, 2022). "The hiPSC-derived brain organoids showed at 9 weeks increased viral particles and infection of microtubule-associated protein 2 (MAP2)-positive mature neurons 24 h post-infection." (PMID 34211370, 2021). "This infection resulted in distinct loss of both MAP2-positive dendrites and neurofilament-positive axons at 24 hours post infection." (PMID 32069324, 2020). "At 24 hours of infection, we observed complete loss of dendritic MAP2 staining." (PMID 32069324, 2020). "At 24 hours of infection, the wildtype neurons displayed complete loss of MAP2-positive neurites." (PMID 32069324, 2020). "Five weeks post-infection, we immunostained the cultures for the neuronal specific marker MAP2 (microtubule-associated protein 2) to determine the number of neurons after each condition." (PMID 40259946, 2025). "Examining the earliest timepoint at which we saw growth defects, 7 days post-infection, we stained organoid sections with antibodies against the transcription factor SOX2 and mitogen-associated protein 2 (MAP2), to image NPCs and neurons, respectively." (PMID 40985448, 2025). "We measured the axonal thickness in MAP2-stained neurons and found that EcoNDK and EcoNL4-3 infection of mixed cell cultures showed an increased axonal thickness from roughly 4.3 μm in uninfected cultures to about 7.8 μm in infected cultures." (PMID 38793575, 2024). "Immunostaining of day 30 and day 60 brain organoids with SOX2+ NSCs and MAP2+ neurons showed a time-dependent increase of nucleoprotein (NP)+ cells compared to mock infection, especially for MAP2+ neurons." (PMID 35910807, 2022). "The pre-synaptic proteins vGLUT1 and Synapsin 1 were decreased by 70% in MAP2+ cells (60% in overall cells) and by 60%, respectively, upon infection with SARS-CoV-2 compared to mock conditions, which were rescued upon treatment with SOF post-infection." (PMID 36327326, 2022). "Immunoreactivity of neuronal cells with anti-MAP2 antibody was qualitatively more prominent in the brain slices prepared from surviving mice inoculated by IM than IC route of infection (A2)." (PMID 34712425, 2021). "In addition, major neuronal loss by decreased MAP-2 expression in both surviving and dead mice might indicate the disintegration of neuronal cytoskeleton and imbalance in CNS milieu which aggravates the infection following SRV infection." (PMID 34712425, 2021). "The IFA results revealed the expression of EV-A71 3Dpol in MAP2 positive neurons over the course of EV-A71 infection." (PMID 32943650, 2020). "Western blotting showed that infection with lyssavirus resulted in significant degradation of MAP2 and neurofilament proteins." (PMID 32069324, 2020). "In this study, infection with rabies virus resulted in increased immunoreactivity of MAP2 and NF-H in the spinal cord of mice." (PMID 29509660, 2018). "The SCI-induced reduction of MAP-2+ dendrites was inhibited by infection with Lenti-shSOCS3 in areas both rostral and caudal to the lesion at 1 and 4 weeks after complete SCI." (PMID 26384335, 2015). "Lenti-pGipz infection followed by complete SCI significantly reduced MAP-2+ dendrites in gray matter and white matter at both 1 and 4 weeks after injury compared to control animals." (PMID 26384335, 2015). "Infected cells were maintained in culture for 2 or 3 weeks post infection (P.I), then fixed and stained for MAP2, a marker of neuronal dendrites." (PMID 26692002, 2015). "Quantitative analyses demonstrated that both Lenti-shSOCS3 and Lenti-shSOCS3 #2 infection decreased SCI-induced loss of MAP-2+ dendrites in both gray and white matter at 1 week after complete SCI when compared to Lenti-pGipz infection." (PMID 26384335, 2015).